WEE1 (WEE1 G2 checkpoint kinase)
Diseases named in the same sentence as WEE1 in open-access papers (continued):
Sharing a sentence is not in itself a finding about the gene and the disease.
tumor (continued). "In addition, WEE1 inhibitors significantly increased the expression of CRT, HMGB1, and other DAMPs in TME, which are closely associated with immunogenic cell death (ICD), suggesting that WEE1 inhibitors may further enhance the efficacy of immunotherapy and induce tumor cell death through ICD." (PMID 37305685, 2023). "Based on these findings, we hypothesized that pharmacological activation of the STING pathway using a STING agonist could enhance the anti-tumour activity of PARP and WEE1 inhibitors." (PMID 37582853, 2023). "This difference might be an advantage for targeting WEE1 instead of ATM and CHK2 to block G2/M arrest in terms of tumor specificity and limited normal tissue toxicity issues." (PMID 36313934, 2023). "Elevated expression of WEE1 and CHK1 in CRPC and NEPC cells and tumor samples." (PMID 37987002, 2023). "In conclusion, our study suggests Wee1 inhibitor adavosertib as a candidate compound to treat HGSOC patients independent of the HR status of the tumor." (PMID 36081565, 2022). "In that report, the authors suggested that modest preferential radiosensitization could be observed by WEE1 and PARP2 inhibitors in the HPV− cell lines, whereas Chk1 inhibitors were more efficient in HPV+ tumor models." (PMID 36612094, 2022). "Indeed, targeted agents against specific components of DNA repair, such as PARP inhibitors, are employed in various tumor types, while others, such as ATR, CHK1 or WEE1 inhibitors, are in clinical development." (PMID 35205700, 2022). "Theoretically, cells with higher Wee1 expression would have a longer doubling time and this may translate in longer PFS and survival in SCLC patients, because their tumor grows more slowly." (PMID 33320980, 2021). "Although DNA repair genes alterations and the resulting genomic instability have been explored in other tumor types, only few DDR inhibitors were employed as monotherapy or combined with chemotherapy in trials enrolling CRC patients, including PARP, WEE1, ATR, and CHK1 inhibitors." (PMID 34201502, 2021). "In support of this, recent work from our group in HGSOC patients demonstrated efficacy of the Wee1 inhibitor adavosertib in combination with gemcitabine, independent of tumour SLFN11 status (NCT02151292)." (PMID 34663950, 2021). "Indeed, the anti-tumor miR-503 suppressed the progression of HCC by targeting the protein arginine methyltransferase 1 (PRMT1) and the WEE1 G2 Checkpoint Kinase (WEE1) to block EMT in HepG2 cells." (PMID 34069740, 2021). "Meanwhile, ZNF300 might activate CDK1 through inhibition of WEE1 and MYT1 and modulation of the MYC/AURKA/BORA/PLK1 axis to promote the tumour cells to overcome G2 arrest and enter the M phase to avoid the apoptosis induced by chemotherapeutic drugs." (PMID 33078469, 2020). "Interestingly, several agents including cyclophosphamide, sorafenib, WEE1 inhibitor AZD1775 and αPD-1 monoclonal antibody showed increased tumor growth inhibition when combined with DN052." (PMID 35006413, 2020). "The activity of WEE1 through the cell cycle can explain its tumor suppressor function, at least in nonmalignant cells." (PMID 32958072, 2020). "Despite reports of additive or synergistic effects in other tumor cell models, combining Wee1 inhibition with irradiation did not reveal an additional therapeutic effect for HNSCC cell lines." (PMID 32047167, 2020). "Tumor regressions were observed only with the combination of Chk1 and Wee1 inhibitors and not with the single agents." (PMID 25428911, 2015). "There was no change in the phosphorylation of CDK1, WEE1 or in the total levels of CDK1 or WEE1 in the tumor samples (data not shown) as expected." (PMID 24661910, 2014).
tumor (continued). "In addition, dose-dependent expression changes of the Wee1 gene signature in rodent xenograft tumors and skin samples were correlated with the level of phosphorylated-CDC2 and anti-tumor efficacy of the Wee1 inhibitor." (PMID 19500427, 2009). "Inhibition of Wee1 could therefore be a potential treatment approach, particularly for tumours lacking FLNA." (PMID 39528354, 2025). "Furthermore, the reduction of Ki67, a proliferation marker, in the test group suggested that WEE1 inhibition failed to drive premature mitosis, resulting in a paused cell cycle and tumor growth suppression." (PMID 40551232, 2025). "During their expansion from this region to other regions, such as clusters 6 and 3 regions, the tumor cells exhibited a more malignant expression pattern, such as high expression levels of malignant markers, such as TNC and TGFBI, as well as active proliferation markers, such as FOS and WEE1." (PMID 39639005, 2024). "Moreover, the use of synthetic lethality extends to exploring combinations such as WEE1 G2 checkpoint kinase (Wee1) and checkpoint kinase 1 (CHK1) inhibitors in neuroendocrine prostate cancer (NEPC), with preclinical mouse models showing effective tumor growth inhibition." (PMID 39204153, 2024). "In non-malignant eukaryotic somatic cells, WEE1 acts as a tumor suppressor." (PMID 37370065, 2023). "Concomitant treatment with a Wee1 inhibitor and an ICI may be a potential therapeutic strategy for the successful treatment of mUC because UC is considered an inflamed and immune-responsive tumor." (PMID 37296592, 2023). "As the preclinical drug testing in organoids helps accurately predict the clinical treatment outcome, the observed efficacy of the multiple low-dose treatment with WEE1 and PKMYT inhibitors suggests that the respective tumours may have responded to the therapeutic combination." (PMID 37325550, 2023). "PARP and WEE1 inhibitors in combination is not sufficient to eradicate BRCA1/2 wild-type TNBC tumours regardless of whether they have low (AT3, 4T1ch9) or moderate (AT3OVA) levels of pre-exsiting TILs." (PMID 37582853, 2023). "Our rationale for investigating these latter targets include prior reports demonstrating that Wee1 is a viable therapeutic target, in combination with chemotherapy, in pre-clinical models of RMS, while MEK inhibition has been shown to have anti-tumor efficacy in pre-clinical FN-RMS models." (PMID 35174853, 2022). "Furthermore, WEE1 inhibition triggered upregulation of STAT1 which induced upregulation of PD-L1 and IFN-γ expression, but upon combination with anti-PD-L1 blockade induced anti-tumor immune response in a CD8+ T cell dependent-manner." (PMID 36551637, 2022). "Interestingly, both WEE1 and ATR inhibitors were shown to affect anti-tumor immune responses after radiation, and simultaneous ATR/WEE1 inhibition together with radiotherapy could potentially be more beneficial in this aspect." (PMID 34359691, 2021). "Since previous experiments found that high iodine can induce the proliferation of BCPAP and 8305C cells by activating AKT/Wee1/CDK1 axis, we discussed whether AKT/Wee1/CDK1 was involved in the tumor growth of xenograft tumor models of PTC and ATC cells induced by high iodine." (PMID 33796458, 2021). "Among positive hits identified, we selected Wee1 kinase as a proof of principle that inhibition of a kinase could increase tumor cell sensitivity to chemotherapy without any increase in DNA damage signaling mark, that is, γH2AX." (PMID 27077811, 2016).
tumor (continued). "The striking differences between responding and non-responding tumor cell lines to Wee1 siRNA could not be easily explained by off-target effects because of the complete lack of efficacy in A549, D54MG and A2780 cells." (PMID 24927813, 2014). "However, WEE1 acts like an oncogene rather than a tumor suppressor in tumor cells." (PMID 37370065, 2023). "These regulatory elements are absent in the WEE1 gene, thereby suggesting a potential biological rationale for PKMYT1 inhibition over WEE1 in HR+ tumours." (PMID 38264947, 2024). "In a therapeutic setting, the quantification of Ki-67 indices revealed significant anti-proliferative effects of adavosertib, a small molecular Wee1-inhibitor, against MUC-1 but not NCI-H295R tumor spheroids." (PMID 35879289, 2022). "Inhibition of WEE1 G2 checkpoint kinase (WEE1), a CDK1 negative-regulator, alongside PD1 blockade resulted in diminished tumour growth in two LUSC subcutaneous syngeneic models." (PMID 34354223, 2021). "Tumor cell sensitivity to cultured murine KIL and human high affinity NK (haNK) cells in the presence or absence of AZD1775, a small molecule inhibitor of WEE1 kinase, was assessed via real time impedance analysis." (PMID 29925431, 2018). "WEE1 and CHK1 inhibition was unable to prevent tumor regrowth, however, suggesting either that not all cells are affected or that following drug treatment cells are able to sufficiently repair damaged DNA." (PMID 23148684, 2012). "WEE1 inhibition with adavosertib monotherapy demonstrated limited clinical activity in patients with SETD2-altered solid tumors despite compelling preclinical data indicating a synthetic lethal effect, which did not translate into robust tumor regression." (PMID 38920407, 2024). "Also, despite the partially overlapping roles of WEE1 and PKMYT1, we did not observe that their expression would be upregulated in mutually exclusive fashion in tumours, supporting the rationale of combined targeting." (PMID 37325550, 2023). "WEE1 and PKMYT1 act as tumor suppressors in non-malignant eukaryotic somatic cells." (PMID 32958072, 2020). "While it is difficult to extrapolate from in vitro tumor cell line suppression to long term clinical benefit in patients, the lack of tumor cell re-growth after combined PLK1 and WEE1 inhibition in our study suggest that this could be an interesting strategy to develop further." (PMID 27558154, 2016).
infection (76 papers, 2009 to 2025). The state of being infected such as from the introduction of a foreign agent such as serum, vaccine, antigenic substance or organism. "Similarly, the infection of human herpesviruses is known to induce cell cycle arrest by enhancing the CDK1 phosphorylation either through perturbing the activities of Wee1 and CDC25C phosphatase or through inactivating the cyclin B-CDK1 complex." (PMID 34756071, 2021). "NN1172-infection leads to the down-regulation of many genes related to cell cycle and DNA replication genes, including MCM 2 ~ 6, CDK1 ~ 2, CCNB2, ANAPC2, MAD2L1, WEE1, RBL1, RB1." (PMID 38362295, 2024). "In contrast to Sox9 and Col2a1, siCdc5l mildly increased the Wee1 pre-mRNA splicing efficiency, and this enhancement was cancelled by AAV-CDC5L infection in ATDC5 chondrocytes." (PMID 34298017, 2021). "Indeed, overexpressing Wee1, a negative regulator of Cdk161, impairs ISC migration after Ecc15 infection." (PMID 34887411, 2021). "The upregulation of WEE1 at 16 DAI, when proliferation dominates, may indicate that it is induced as a feedback to limit excessive proliferation, or it may be due to the heterogenous nature of infection with some early colonised cells already being driven to hypertrophy." (PMID 30431210, 2019).
neurodegenerative disease (19 papers, 2007 to 2025). A disorder of the central nervous system characterized by gradual and progressive loss of neural tissue and neurologic function. "These include Spon2, Adam19, Arntl, Cdkn1a, Cry2, Per2, Per3, Wee1, Rcan1, Slc41a3, Errfi1, and Bhlhe41, which are related to numerous cardiovascular and degenerative diseases of other organs as well as varying aging processes." (PMID 33668521, 2021).
hematological malignancies (7 papers, 2015 to 2025). "Both CDK1 and WEE-1 inhibitors are currently being used in clinical trials for the treatment of hematologic malignancies (below)." (PMID 25914884, 2015). "Little has been reported about the activity of Chk1 and Wee1 inhibitors in hematologic malignancies." (PMID 25428911, 2015).
WEE1 also shares sentences with these, for which no sentence is quoted: myotonic dystrophy type 1 (35 papers); diabetes (32); Insulin resistance (31); Parkinson disease (29); Obesity (16); type 2 diabetes (14); ataxia telangiectasia (11); COVID-19 (11); autoimmune disease (10); depression (10); Anxiety (9); neurological disorders (9); heart failure (8); Hepatic steatosis (8); Hypertension (8); myotonic dystrophy (8); Stroke (8); genetic disorder (7); metabolic disease (7); renal cell carcinoma (7); amyotrophic lateral sclerosis (6); cardiac hypertrophy (6); Down syndrome (6); Hyperglycemia (6); myocardial infarction (6); pulmonary fibrosis (6); rheumatoid arthritis (6); Sepsis (6); asthma (5); autism (5).
A further 302 diseases each share a sentence with WEE1 in 5 papers or fewer.